MTOR (mechanistic target of rapamycin kinase)
Diseases named in the same sentence as MTOR in open-access papers (continued):
Sharing a sentence is not in itself a finding about the gene and the disease.
cancer (continued). "Researchers are exploring combination therapy that inhibits both MYC and mTOR to improve treatment outcomes for MYC-driven cancer." (PMID 39779613, 2025). "The SESN2/AMPK/mTOR pathway is essential for regulating cellular energy metabolism, stress response, and cancer progression." (PMID 40775338, 2025). "It was observed that macropinocytosis in cancer cells activates the mTOR signaling pathway, which promotes the expression of PD-L1 and inhibits T cell activation and function, thereby leading to immune escape of cancer cells." (PMID 40723808, 2025). "The precise regulation of the PI3K/AKT/mTOR pathway is of paramount importance in fields such as cancer research, where aberrant activation of this signalling cascade has been strongly implicated in the initiation and progression of multiple malignancies." (PMID 40429821, 2025). "Another potential target of β-elemene is the protein kinase B (Akt)-mechanistic target of rapamycin (mTOR) signaling pathway, essential for regulating cell growth and frequently dysregulated in cancer cells." (PMID 41399412, 2025). "In contrast to other types of cancer, very few mutations are found in the main components of the PI3K/AKT/mTOR signaling pathway in acute leukemias." (PMID 40725184, 2025). "Many cancer types typically exhibit dysregulation of the PI3K/Akt/mTOR signaling pathway, which affects multiple processes, including cell survival and proliferation, metabolism, angiogenesis, and metastasis." (PMID 40227591, 2025). "HBx enhances the Warburg effect by activating the PI3K/Akt/mTOR signalling pathway, thereby up‐regulating the expression of cancer cell stemness‐related proteins." (PMID 40717222, 2025). "Key metabolic pathways are tightly linked to cancer development, including insulin signaling, insulin‐like growth factor‐1 (IGF‐1), and mTOR." (PMID 40777199, 2025). "Phosphatidylinositol 3-kinase (PI3K)/protein kinase B (AKT)/mammalian target of rapamycin (mTOR) signaling pathway is among the most frequently activated pathways in various human cancers, crucially contributing to the initiation and progression of tumors." (PMID 39877641, 2025). "PI3K/AKT/mTOR pathway abnormalities are present in about 50% of malignancies and are the most frequently activated pathways in human cancer." (PMID 40717210, 2025). "AuNPs suppress autophagy by targeting the AKT/mTOR pathway, a vital mechanism for cancer cell survival under stress." (PMID 40076496, 2025). "This positions the PI3K/AKT/mTOR axis as a linchpin integrating external cues with the internal machinery controlling cell fate and metabolism, making it indispensable for many cancer hallmarks." (PMID 40740483, 2025). "Increasing evidence suggests that mTOR signaling pathways play an important role in cancer cell proliferation, migration, invasion, and glucose metabolism." (PMID 40278414, 2025). "The relationship between mTOR and mitochondrial dynamics has been shown to be important in diverse cellular contexts, including neurodegenerative diseases, cancer, and metabolic disorders." (PMID 40450326, 2025). "Akt1 plays a crucial role in the PI3K/Akt/mTOR signaling pathway, which is often dysregulated in numerous human cancers." (PMID 40798865, 2025). "In cancer, mTOR is often activated, stimulating cancer cell growth, promoting adaptive evolution, and driving tumor metabolic reprogramming through the re-regulation of glucose, amino acids, nucleotides, fatty acids, and lipid metabolism." (PMID 39963130, 2025). "Suberoylanilide hydroxamic acid (SAHA), a potential treatment and HDAC inhibitor, induced autophagy in cancer cells while blocking the Akt/mTOR pathway and inducing the endosplasmic reticulum stress response." (PMID 41151762, 2025).
cancer (continued). "The PI3K/AKT/mTOR pathway is a crucial signaling network that, when disrupted, promotes increased cellular growth, survival, and metabolism, thereby giving cancer cells a proliferative edge." (PMID 41164768, 2025). "Intracellular signaling pathways such as ALK, BRAF/MEK, and PI3K/AKT/mTOR are essential for the growth and survival of cancer cells." (PMID 40872476, 2025). "Studies across different cancers have demonstrated that modulation of the PI3K/AKT/mTOR axis can affect both survival and toxic autophagy." (PMID 40740483, 2025). "Beyond immune evasion, PD-L1 has intrinsic roles in cancer cells, including promoting tumor proliferation by activating the AKT/mTOR signaling pathway, contributing to cancer stemness, and facilitating metastasis by promoting EMT phenotypes." (PMID 40389855, 2025). "The abnormal activation of the PI3K/Akt/mTOR signaling pathway has been extensively studied in various cancers, particularly in NSCLC." (PMID 40328748, 2025). "Utilizing small molecule inhibitors (e.g., PI3K, AKT, and mTOR inhibitors) to target this system has emerged as a viable method for cancer therapy." (PMID 40076496, 2025). "Dysregulation of this pathway is implicated in various diseases, notably in cancer where mutations in PI3K, loss of the tumor suppressor PTEN, or overactivation of AKT/mTOR drive tumor growth." (PMID 40773107, 2025). "By activating the mTOR signaling pathway, cancer cells can continue to support cell survival and proliferation, circumventing the inhibitory effects of CDK4/6 inhibitors." (PMID 40303296, 2025). "The significance of AKT/mTOR signaling activation in cancer progression has been elucidated in numerous previous studies, including our own." (PMID 39425259, 2025). "NVP-BEZ235 is a dual PI3K/mTOR whose mechanism of action is based on promoting cancer cells to apoptosis." (PMID 40042556, 2025). "In cancer cells, the mTOR/Akt signaling pathway is frequently overactivated, contributing to tumor development and progression." (PMID 40287470, 2025). "PI3K/AKT/mTOR pathway dysregulation makes cancer cells particularly vulnerable to this approach, leading to substantial reductions in protein synthesis and proliferation rates." (PMID 40805165, 2025). "A key feature in cancer progression is the overactivation of the cell cycle mediated by EGFR signaling pathways such as PI3K/Akt/mTOR and RAS/RAF/MEK/ERK." (PMID 40943615, 2025). "In summary, metabolic reprogramming in cancer is regulated by miRNAs, which in turn regulate the canonical metabolic pathways of malignant transformation and progression such as mTOR, AMPK, and SIRT." (PMID 40149420, 2025). "Since 2000, scientists have been attempting to create trustworthy stand‐in indicators to gauge how well mTOR inhibitors are performing as cancer treatments." (PMID 40717210, 2025). "Nanoparticle-based drugs delivery methods possess significant potential to influence the PI3K/AKT/mTOR pathway and control autophagy in cancer." (PMID 40076496, 2025). "The PI3K/AKT/mTOR signaling axis is crucial in cancer progression, regulating cell growth, survival, and metabolism." (PMID 40740483, 2025). "Studies have found that the dysregulation of the mTOR signaling pathway is closely related to a variety of diseases, including cancer, intestinal inflammation, aging, and so on." (PMID 39942843, 2025). "In vitro, in vivo, and clinical trial experiments have shown that inhibition of mTOR has therapeutic efficacy against cancer." (PMID 40647460, 2025). "The mTOR/AKT/PI3K cascade represents a crucial signaling system that is often dysregulated in various human cancers." (PMID 40754657, 2025). "The PI3K/AKT/mTOR pathway has been identified as a regulator of ferroptosis, and its downregulation increases ferroptosis in cancers." (PMID 40740483, 2025).
cancer (continued). "By unraveling the intricate molecular interactions between bioactive compounds, the mTOR signaling pathway, autophagy activation, and monitoring mTOR activity, our understanding of cancer biology can significantly advance." (PMID 40717210, 2025). "This section focuses on the interaction between the PI3K/AKT/mTOR axis and autophagy in human cancers." (PMID 40740483, 2025). "mTOR inhibitors are currently approved to treat various cancers, such as renal cell carcinomas, neuroendocrine tumours, and breast cancer and have shown promise as a treatment option for pBTs, both in pre-clinical and clinical settings." (PMID 41471075, 2025). "PIK3R1 is a regulatory subunit of the PI3Ks, which are part of the PI3K/AKT/mTOR pathway, a critical pathway in cancer that regulates cell survival and growth." (PMID 40869429, 2025). "For example, SalB exerts anti-fibrotic effects via the CD36/PI3K/AKT pathway while simultaneously exhibiting antioxidant, anti-inflammatory, and anti-cancer effects through the AKT/mTOR pathway, thereby establishing a multi-layered regulatory mechanism." (PMID 41357244, 2025). "High levels of IGF-1R can cause resistance across different cancers, and cancer cells can become resistant to IGF-1R inhibitors, by activating PI3K/mTOR pathways through alternative EGFR signaling." (PMID 41427337, 2025). "This downregulation correlates with the inhibition of key downstream signaling pathways, including MAPK and Akt/mTOR, which are critical for cancer cell proliferation and survival." (PMID 41098412, 2025). "Compared with Basal-like BRCA, Luminal A and B and Her2-enriched cancer had a slightly higher CS in terms of the TSC/mTOR pathway (Basal-like: 0.3; Luminal A and B: 0.6; Her2-enriched: 0.4)." (PMID 39954675, 2025). "The PI3K/Akt/mTOR pathway influences cancer development by regulating key processes such as apoptosis, transcription, translation, metabolism, angiogenesis, and cell cycle progression." (PMID 41304968, 2025). "The activation of MAPK/ERK and Akt/mTOR promotes the proliferative activity of cancer cells by regulating autophagy." (PMID 40123978, 2025). "Arginine is synthesized from citrulline and acts as a direct activator of mTOR that strongly activates proliferation and metastasis of the cancer cells." (PMID 40374694, 2025). "Given that various signaling pathways, including TGF-β, NF-κB, and PI3K/AKT/mTOR pathways, influence cancer progression, their activity and significance can vary depending on the cancer type." (PMID 40075635, 2025). "This aligns with the broader impact of metformin on the PI3K/AKT/mTOR signaling axis, which is also critical for cancer cell metabolism and survival." (PMID 40387523, 2025). "Disrupting the mTOR pathway contributes to uncontrolled cell growth, increased proliferation, and enhanced cell survival, all of which are hallmarks of cancer." (PMID 40717210, 2025). "Overall, the findings from both spheroids and organoids treated with Res derivatives indicate that SM-3 offers a novel strategy for anticancer drug development by targeting cancer stem cells through mTOR inhibition." (PMID 40287470, 2025). "Dysregulation of the PI3K/Akt/mTOR pathway promotes aberrant proliferative signaling and disrupts cellular metabolic homeostasis, which are hallmarks of cancer." (PMID 40666093, 2025). "Increasing evidence has highlighted the role of the PI3K/AKT/mTOR pathway in modulating autophagy in cancers." (PMID 40740483, 2025). "NR2F1 has been previously reported to induce tumor dormancy and inhibit mTOR signaling in several cancer models." (PMID 40955663, 2025). "There are several mTOR inhibitors being studied and developed to have enhanced selectivity and robust anti-cancer effects." (PMID 40407951, 2025). "FA loss stimulated amino acid accumulation, translation, and protein production via mTOR signaling, which is reported to promote cancer development and progression." (PMID 40805278, 2025).
cancer (continued). "A disintegrin‐like and metalloprotease with thrombospondin type 1 motif 9 (ADAMTS9) encodes a zinc metalloprotease that has been shown to function as a tumour suppressor in other cancer models leading to downregulation of the AKT/mTOR pathway." (PMID 40135438, 2025). "Since then, mTOR has been extensively studied, with many studies demonstrating that its activity is often abnormally elevated in cancer." (PMID 40299431, 2025). "The AKT/mTOR signaling pathway can promote glycolysis and lactate production, playing a key role in the metabolic reprogramming of cancer cells." (PMID 39910045, 2025). "The PI3K/AKT/mTOR pathway as a key regulator of cancer cells has become a promising target for potential anti-cancer development." (PMID 41180483, 2025). "Several mTOR-related metabolic, immune, and gut microbiota traits have been identified as potential novel cancer targets, though more extensive experimental studies and clinical trials are needed to confirm these findings." (PMID 40299431, 2025). "While PI3Kδ is predominantly expressed in immune cells, gain-of-function mutations can cause hyperactivation of the mTOR pathway, contributing to disorders like activated PI3K-δ syndrome (APDS) and certain cancers." (PMID 40358185, 2025). "The PI3K/AKT/mTOR signaling axis is a central driver of oncogenesis, fundamentally intertwined with the core pathways and biological mechanisms defining cancer." (PMID 40740483, 2025). "In fact, mTOR inhibition increases PD-L1 expression on tumor endothelial cells, facilitating cancer immune escape." (PMID 40647529, 2025). "Fatty acids and phospholipids act as signaling molecules that activate key oncogenic pathways, such as the PI3K/Akt/mTOR pathway, enhancing the survival, migration, and invasion capabilities of cancer cells." (PMID 40391753, 2025). "The PI3K/AKT/mTOR pathway is essential for cancer cell motility, proliferation, survival, and metabolism." (PMID 40487371, 2025). "Among the key regulators of amino acid homeostasis and protein synthesis in cancer is the mechanistic target of rapamycin (mTOR) signaling pathway." (PMID 40805278, 2025). "The mTOR protein is crucial in regulating cellular metabolism and is frequently hyperactivated in many cancers, particularly lung cancer." (PMID 40287470, 2025). "Rapamycin, a well-known mammalian target of rapamycin (mTOR) inhibitor, has demonstrated considerable anti-cancer potential, particularly in inhibiting tumor cell proliferation, blocking angiogenesis, and inducing autophagy." (PMID 40361560, 2025). "Activation of AMPK leads to the inhibition of mTOR and the promotion of fatty acid oxidation and glucose uptake, creating an unfavorable environment for cancer cell growth." (PMID 39940361, 2025). "The mTOR pathway, a key regulator of cell growth and metabolism, enhances glutamate influx and metabolism in cancer cells, making it a potential therapeutic target." (PMID 40567251, 2025). "When both are overexpressed, their interaction inhibits the Warburg effect (aerobic glycolysis providing energy to cancer cells) by suppressing the PI3K/Akt/mTOR pathway, thereby restricting cancer progression." (PMID 39714760, 2025). "PI3K inhibitors target the PI3K/mTOR pathway which many cancers depend on to survive, while HSP90 inhibitors destabilize several oncogenic proteins, both leading to tumor cell death." (PMID 41282100, 2025). "We describe the role of the PI3K/AKT/mTOR axis in regulating major hallmarks of cancer, including survival, metabolic reprogramming, angiogenesis, and immune evasion." (PMID 40740483, 2025). "mTOR is frequently found to be hyperactivated in human cancers, and the mechanisms behind its regulation are of great interest for the development of new treatments." (PMID 40653822, 2025). "Signaling pathways involved in dormancy include the PI3K/AKT/mTOR pathway, which is frequently dysregulated in cancer and often downregulated in dormancy, leading to decreased protein synthesis and cell cycle arrest." (PMID 40732251, 2025).
cancer (continued). "The selection of NPRL3, a component of the GATOR1 complex involved in mTOR signaling regulation, aligns with known dysregulation of growth signaling pathways in cancer." (PMID 40227838, 2025). "It is noteworthy that metformin enhances the effectiveness of chemotherapy in fighting cancer by targeting mTOR pathway." (PMID 40769273, 2025). "Despite the critical roles of both Ephexin1 and mTOR signaling in cancer progression, their functional relevance remains largely unexplored." (PMID 40855114, 2025). "The mTOR signaling pathway in cancer cells drives G-CSF expression, stimulates MDSC accumulation, and promotes tumor progression." (PMID 41368628, 2025). "has shown that DPP-4I promotes epithelial-mesenchymal transition through the CXCL12/CXCR4/mTOR axis, thereby inducing cancer progression and metastasis." (PMID 40040724, 2025). "This condition shares several characteristics with cancer, including tissue invasion, resistance to apoptosis, genetic alterations and activation of pathways like mTOR." (PMID 40550987, 2025). "The process of fatty acid synthesis is frequently upregulated in cancer, with both fatty acid synthesis and uptake stimulated in response to mTOR signaling." (PMID 40641601, 2025). "Compound 36 inhibited glucose uptake and lactate production in several cancer cell lines by downregulating PKM2 expression through the inhibition of the mTOR-HIF1α axis." (PMID 40941984, 2025). "Different types of cancers upregulate the mammalian target of rapamycin (mTOR) signaling which can contribute to tumor development and progression by increasing cell proliferation and survival." (PMID 40702333, 2025). "The PI3K/AKT/mTOR signaling pathway is a central regulator of cell survival, growth, metabolism, and proliferation, playing a crucial role in normal physiology and cancer progression." (PMID 40722714, 2025). "Among the top 5 pathways identified in the RNA-Seq analysis, the AMPK signaling pathway, known for negatively regulating the mTOR pathway and thereby inhibiting cancer cell survival and proliferation, was significantly downregulated (top)." (PMID 40526430, 2025). "EA has also been demonstrated to inhibit the activation of key signaling kinases, such as the phosphorylated form of STAT3, Akt kinase, and ERK1/2, thereby leading to the inhibition of the PI3K/Akt/mTOR pathway, which is often overactive in cancer cells." (PMID 40572559, 2025). "Several well-known clients of HSP90 are members of the PI3K/AKT/mTOR pathway; protein kinases that have been targeted in multiple cancers including ACC." (PMID 41282100, 2025). "The interplay between the PI3K/AKT/mTOR pathway and autophagy forms a vital axis in cancer growth and therapeutic response, as highlighted in studies across various tumor types." (PMID 40740483, 2025). "The interplay of DNA damage, its repair, and the mTOR pathway has been the subject of numerous studies, specifically in the field of cancer biology." (PMID 40392611, 2025). "The expression of IL34 was not predictive of the response to the previous RCC standard-of-care mTOR inhibitor everolimus, which exerts a wide range of anti-neoplastic effects by targeting cancer and stromal cells." (PMID 40538439, 2025). "Apart from mTOR, Raf, which is dysregulated in cancer, is also a likely relevant target for survival signals provided by PLD and PA." (PMID 41284888, 2025). "And several generations of mTOR inhibitors have been developed, showing great potential in cancer therapy." (PMID 40299431, 2025). "In contrast, the mechanism by which mTOR inhibitors influence BMI reduction differs from their role in cancer." (PMID 40299431, 2025). "mTOR inhibitors indeed have immunosuppressive and anti-cancer effects, making them interesting in the treatment of post-transplant cancers." (PMID 40590038, 2025). "Backgrounds: This study explores the design of substituted tetrahydroquinoline (THQ) derivatives and their synthesis as possible inhibitors of mTOR inhibitors for targeted cancer therapy." (PMID 40075606, 2025).